KLF12 (KLF transcription factor 12)
Diseases named in the same sentence as KLF12 in open-access papers (continued):
Sharing a sentence is not in itself a finding about the gene and the disease.
cancer (33 papers, 2014 to 2026). A tumor composed of atypical neoplastic, often pleomorphic cells that invade other tissues. "Recent studies have pointed to the role of Krüpple‐like factor 12 (KLF12) in cancer‐associated processes, including cancer proliferation, apoptosis, and metastasis." (PMID 37606530, 2023). "Low KLF12 enhanced the tumorigenic capacity of cancer cells and was associated with poor survival." (PMID 38560274, 2024). "This haplotype block included the long non-coding RNA LINC00402 and KLF Transcription Factor 12 (KLF12) gene, which encodes a protein that is a member of the Krüppel-like zinc finger protein family and has been broadly associated with various other cancers types." (PMID 37509244, 2023). "Aberrant KLF12 expression has been associated to several types of cancers." (PMID 28328537, 2017). "Increasing evidence has shown that KLF12 has an important role in several kinds of cancer by affecting different biological processes." (PMID 37156774, 2023). "KLF12 has been reported to be responsible for the function of circRNA via miRNA in cancer regulation." (PMID 34616917, 2021). "Krueppel-like factor 12 (KLF12) is a member of the KLFs’ family and plays essential roles in various human cancers, including GC." (PMID 34461926, 2021). "KLF12 has been reported as an important TF that participates in the tumorigenesis of various cancers." (PMID 34950609, 2021). "This suggests that this inverse relationship between miR-141 and KLF12 is generally found in human cancers." (PMID 28095864, 2017). "Such inverse relationship between miR-141 and KLF12 is also confirmed in other human cancer types according to TCGA database." (PMID 28095864, 2017). "Kruppel like factor 12 (KLF12) has potential oncogenic effects in a variety of cancers." (PMID 36121916, 2022). "KLF12 is a member of the Krüppel-like factor family, and its overexpression directly affects proangiogenic processes via transcriptional regulators participating in a multitude of cancer-relevant processes." (PMID 36213124, 2022). "Furthermore, in the present study, overexpression of bta-miR-149-5p significantly (p < 0.05) upregulated LIPG (endothelial lipase) and KLF12 expression, which perform vital roles in cancer." (PMID 33922274, 2021). "Studies have shown that KLF12 regulates proliferation of cancer cell lines." (PMID 33937014, 2021). "Similarly, HPV integration appeared to have occurred in the intron of a gene involved in cellular processes such as the Kruppel-like factor 12 (KLF12) or the coding gene for the E1A binding protein p300 in a carcinoma (B8) or an ASCUS (C10), respectively." (PMID 30728408, 2019). "A high level KLF12 expression in the cancer cells or tissue may indicate a poor prognosis." (PMID 37156774, 2023). "This sponging leads to the subsequent upregulation of BMI1, KRAS, AKT3, KLF12, and NAMPT, along with several other cancer-promoting genes, thus promoting a more aggressive phenotype." (PMID 39039064, 2024). "We also analyzed a panel of putative cancer-related genes, including CDK8, MITF, SMAD7, KLF12, AG02, CDK14, and BCL-9, but only PTEN expression was shown to be significantly altered by miR-216a overexpression." (PMID 30061175, 2018). "For cancer, identified targets include VEGFB, VEGFR2, MAP2, MMP14, HNF1A, TUSC5 and KLF12." (PMID 35356223, 2022). "However, the comprehensive regulatory network of KLF12 in cancer has not been fully elucidated." (PMID 37156774, 2023). "miR-484 is a key factor in cancer and non-cancerous diseases, and its targets in cancer include VEGFB, VEGFR2, MAP2, MMP14, HNF1A, TUSC5, and KLF12." (PMID 36572856, 2022). "Pan‐cancer analysis using starBase v3.0 project observed negative correlation between ISG15 and KLF12 in multiple cancers." (PMID 33797839, 2021).
cancer (continued). "Six of the 10 remaining genes, despite not being listed, were genes for which literature search supported undeniable oncogenic properties (STIM2, ARHGAP24, KLF12, KMT2C, CCDC88C and DOCK11), and 4 genes were—to our knowledge—not previously reported in cancer, yet may include new candidate drivers." (PMID 28534499, 2017).
infection (4 papers, 2015 to 2024). The state of being infected such as from the introduction of a foreign agent such as serum, vaccine, antigenic substance or organism. "An appropriate trophoblast-epithelial cell interaction model confirmed that Ishikawa cell infection with Ad-Flag-KLF12 resulted in a significant reduction in BeWo spheroid adhesion." (PMID 30109142, 2018). "Infection of hESCs with Ad-Flag-KLF12 (MOI = 25 and 50) for 48 h markedly increased KLF12 mRNA expression (by greater than 110-fold and 200-fold, respectively)." (PMID 26223982, 2015).
adenocarcinoma (3 papers, 2021 to 2024). A common cancer characterized by the presence of malignant glandular cells. "While analyzing these CRPC-adenocarcinoma and t-NEPC patients’ individual expression for Pax5, ETV5 and KLF12, we further found that both ETV5 and KLF12 expression vary among adenocarcinoma and t-NEPC patients, with sometimes showing higher expression in CRPC adenocarcinoma." (PMID 39183332, 2024).
gynecological tumor (2 papers, 2021 to 2023). "We next used the GEPIA website based on the TCGA database and analyzed the expression of KLF12 in the three major gynecological tumors." (PMID 34950609, 2021).
KLF12 also shares sentences with these, for which no sentence is quoted: adenovirus infection (1 paper); adolescent idiopathic scoliosis (1); alcohol dependence (1); cardiovascular diseases (1); intestinal cancer (1); leukemia (1); lung adenocarcinoma (1); lung disease (1); Pan (1); prostate carcinoma (1); Stroke (1); type 2 diabetes (1).